MVK (mevalonate kinase)
Diseases named in the same sentence as MVK in open-access papers (continued):
Sharing a sentence is not in itself a finding about the gene and the disease.
periodic fever syndrome (14 papers, 2013 to 2025). Fevers of unknown etiology recurring over months or years. "HIDS with periodic fever syndrome is an autosomal recessive disease caused by a mutation of the MVK gene, leading to reduced mevalonate kinase enzymatic activity." (PMID 40376361, 2025). "The third nonsynonymous likely pathogenic variant in the MVK i.e., V377I, had been reported in various studies as a cause of Hyperimmunoglobulinemia D with Periodic Fever Syndrome (HIDS) (OMIM number 260920)." (PMID 34054914, 2021). "Biallelic mutations in MVK cause the more severe, systemic disease, hyperimmunoglobulinemia D and periodic fever syndrome, and heterozygous mutations in MVK lead to porokeratosis." (PMID 32153585, 2020). "Mevalonate kinase deficiency (MKD) is a rare periodic fever syndrome with autosomal recessive inheritance that is caused by a mutation in the MVK gene encoding mevalonate kinase (MK)." (PMID 27652005, 2016). "Indeed, one of the porokeratosis-causative mevalonate pathway genes, MVK, is also causative of hyperimmunoglobulinemia D and periodic fever syndrome, an established autoinflammatory syndrome." (PMID 32153585, 2020). "The main differential diagnoses include other periodic fever syndromes such as TRAPS, cryopyrin-associated periodic syndromes (CAPS), and mevalonate kinase deficiency." (PMID 41523473, 2025). "In these patients, a genetic examination was carried out for monogenic periodic fever syndromes and the occurrence of non-pathogenic variants in MEFV and MVK genes were confirmed." (PMID 38143757, 2023).
cryopyrin-associated periodic syndrome (13 papers, 2015 to 2025). Cryopyrin associated periodic syndrome (CAPS) defines a group of autoinflammatory diseases, characterized by recurrent episodes of systemic inflammatory attacks in the absence of infection or autoimmune disease. "Arthritis was also present in two patients with cryopyrin-associated periodic syndrome (CAPS) and one patient with mevalonate kinase deficiency (MKD)." (PMID 40933983, 2025). "TNRSF1A, NLRP3 and MVK gene mutations are associated with three other hereditary recurrent fevers, namely TNF-α receptor-associated periodic syndrome (TRAPS), cryopyrin-associated periodic syndromes (CAPS) and mevalonate kinase deficiency." (PMID 37504266, 2023). "MVK mutation-induced hyperimmunoglobulin D syndrome (HIDS) and NLRP3 mutation-induced cryopyrin-associated periodic syndrome (CAPS) have been added to the spectrum of SAIDs." (PMID 35123508, 2022). "The best known HRF are Familiar Mediterranean Fever (FMF), Cryopyrin-Associated Periodic Syndrome (CAPS), TNF-receptor associated periodic fever syndrome (TRAPS) and Mevalonate-Kinase Deficiency (MKD), caused by mutations in MEFV, NLRP3, TNFRSF1A and MVK genes, respectively." (PMID 29047407, 2017).
autoinflammatory syndrome (6 papers, 2015 to 2025). A group of disorders of the innate immune system characterized by attacks of seemingly unprovoked inflammation without significant levels of either autoantibodies or autoreactive T cells more characteristic of autoimmune disease. "Hyper-IgD is an autoinflammatory syndrome caused by a mevalonate kinase deficiency (MKD), a key kinase in the sterol and isoprenoid production pathway." (PMID 35720358, 2022). "In addition, one patient was diagnosed with X-linked immunodeficiency with magnesium defect, Epstein–Barr virus infection and neoplasia due to a hemizygous MAGT1 variant; another newborn was diagnosed with auto-inflammatory syndrome caused by MVK variants." (PMID 34677667, 2021). "In a previous study, using a next generation sequencing approach, we found many rare variants and some functional polymorphisms in genes related to autoinflammatory syndromes (AID): CECR1, MEFV, MVK, NLRP3, NOD2, PSTPIP1 and TNFRSF1A in our BD cohort." (PMID 30808881, 2019). "IL-1β, IL-18, and IL-33 were within normal limits or undetectable, and no mutations were found in genes related to the pathogenesis of autoinflammatory syndromes (MEFV, MVK, TNFRSF1A, NLRP3, and NLRP12)." (PMID 34829952, 2021).
porokeratosis (5 papers, 2015 to 2024). A clonal proliferation of abnormal keratinocytes characterized by the development of localized or multiple atrophic skin patches surrounded by an annular keratotic ring called cornoid lamella. "A possible causative link between MVK mutations and porokeratosis is that mevalonate kinase prevents UVA-induced apoptosis in keratinocytes." (PMID 25990874, 2015). "Interestingly, one of the major causative genes of porokeratosis, MVK, is also known to be causative of a conventional autoinflammatory disease, hyperimmunoglobulinemia D, and periodic fever syndrome (MIM 260920)." (PMID 32425927, 2020). "To date, four mevalonate pathway genes (MVK, MVD, PMVK, and FDPS) have been identified as causative of porokeratosis." (PMID 32153585, 2020). "In a Chinese family with porokeratosis of Mibelli, a dermatological disease closely related to DSAP, a novel splice site mutation in MVK was found." (PMID 25990874, 2015). "Notably, the PM subtype of porokeratosis shows particular alterations in the MVK and PMVK genes, resulting in decreased expression of the respective enzymes." (PMID 39219867, 2024).
Ataxia (4 papers, 2016 to 2026). Ataxia refers to impaired coordination of voluntary muscle movement. "Mevalonate kinase (MK) deficiency is a rare autosomal recessive metabolic disorder caused by pathogenic variants in the MVK gene with a broad phenotypic spectrum including autoinflammation, developmental delay and ataxia." (PMID 36636591, 2022). "In patients with mevalonic aciduria due to complete MVK deficiency, neurological manifestations may include dysmorphic craniofacial features, psychomotor retardation, developmental delay, hypotonia and progressive cerebellar ataxia." (PMID 30026765, 2018).
inflammatory bowel disease (4 papers, 2021 to 2025). A spectrum of small and large bowel inflammatory diseases of unknown etiology. "Variants in MVK have also been linked to retinitis pigmentosa (RP) and early onset inflammatory bowel disease (IBD)." (PMID 34539662, 2021). "Alterations of this pathway, such as mevalonate kinase deficiency (MKD), lead to inflammatory bowel disease, or IBD-like intestinal inflammation, possibly due to decreased immunosuppressive isoprenoid intermediates formed through the mevalonate kinase pathway." (PMID 36604447, 2023). "In the presence of a “true” and recurrent buccal and/or genital aphthosis, the following may be considered: idiopathic recurrent benign buccal aphthosis, inflammatory bowel disease (IBD), Mendelian autoinflammatory syndromes (HA20, mevalonate kinase deficiency MKD), and Behçet-like syndromes." (PMID 33622338, 2021).
cervical lymphadenitis (3 papers, 2020 to 2025). Inflammation of the cervical lymph nodes. "Diagnosis is made by confirming the presence of a pathological MVK genotype and at least one of the following signs: gastrointestinal disturbances, cervical lymphadenitis, or aphthous stomatitis." (PMID 41333465, 2025).
cobalamin deficiency (3 papers, 2016 to 2017). "Recent GWASes have found several novel loci at chromosome 12q24, including the mevalonate kinase (MVK) and methylmalonic aciduria (cobalamin deficiency) cblB type (MMAB) genes, both of which influence high-density lipoprotein cholesterol (HDL-C) levels." (PMID 29069827, 2017). "Little is known about the association of the mevalonate kinase (MVK), methylmalonic aciduria (cobalamin deficiency) cblB type (MMAB) single nucleotide polymorphisms (SNPs) and serum lipid levels." (PMID 29050287, 2017).
colitis (3 papers, 2015 to 2022). Inflammation of the colon. "Afterwards, the association of early colitis with recurrent fever, rash and splenomegaly arouse the suspicion of Mevalonate Kinase Deficiency, yet genetic analysis excluded the presence of the disease." (PMID 26671016, 2015). "IL-1 receptor antagonist has been shown to ameliorate colitis in a Mendelian type of IBD, driven by mutations in the mevalonate kinase pathway." (PMID 35731827, 2022). "Furthermore, while experimental colitis upregulated inflammatory genes in the colon, including Tnfa, Il6 and Ifng, UC patients also upregulated IL17A and IL10, followed by a slight increase in IL4 and mevalonate kinase (MVK) expression." (PMID 34434187, 2021).
PFAPA syndrome (3 papers, 2015 to 2023). An auto inflammatory syndrome characterized by recurrent febrile episodes associated with aphthous stomatitis, pharyngitis and cervical adenitis. "DNA of patients with PFAPA syndrome was analyzed for the 3 genes associated with monogenic periodic fever (NLRP3, MEFV, and MVK) and for the AIM2 gene." (PMID 25821352, 2015).
anaemia (2 papers, 2016 to 2022). "Mevalonate kinase deficiency was suspected on the basis of clinical (hydrops fetalis, hepatosplenomegaly, hypotonia) and laboratory signs (anaemia, intense acute phase reaction, increased urinary excretion of mevalonic acid)." (PMID 27012807, 2016).
autoimmune disease (2 papers, 2024 to 2025). A disorder resulting from loss of function or tissue destruction of an organ or multiple organs, arising from humoral or cellular immune responses of the individual to their own tissue constituents. "In MVK deficiency – a rare autoimmune disorder caused by mutations in the MVK gene – mevalonate, a cholesterol precursor, accumulates in patient macrophages and induces heightened inflammatory responses." (PMID 38129659, 2024). "Dysfunctional cholesterol metabolism has also been linked to inherited autoimmune diseases such as mevalonate kinase (MVK) deficiency." (PMID 38129659, 2024). "STX8 and YES1 are implicated in T-cell activation, MAP4K5, RRM2B, FOXO1, ERBB2IP and INPPL1 can promote inflammation and KIM1, MVK and BANK1 have been associated with autoimmune diseases." (PMID 40247373, 2025).
dyslipidemia (2 papers, 2016 to 2017). "We systematically selected and genotyped 18 potentially functional polymorphisms in MVK, MMAB and KCTD10 by using the TaqMan OpenArray Genotyping System in a Chinese population including 399 dyslipidemia cases, 697 CHD cases and 465 controls." (PMID 27716295, 2016). "To determine whether polymorphisms in MVK, MMAB and KCTD10 are independently associated with the risk of dyslipidemia and CHD, we conducted a case–control study with 399 dyslipidemia cases and 465 controls in Han Chinese." (PMID 27716295, 2016). "Therefore, MVK, MMAB and KCTD10 genes may be candidates as susceptibility genes modulating HDL-C concentrations and then affect the risk of dyslipidemia and CHD." (PMID 27716295, 2016).
hydrops fetalis (2 papers, 2016 to 2025). Hydrops fetalis is a severe and challenging fetal condition usually defined as the excessive accumulation of fetal fluid within the fetal extravascular compartments and body cavities that manifests as edema, pleural and pericardial effusion and ascites. "Here, we report the case of a preterm infant born at 30 + 2 weeks of gestation with a prenatal genetic diagnosis of mevalonate kinase deficiency presenting with intrauterine bowel dilatation, mild hydrops fetalis, and microcephaly." (PMID 40038796, 2025).
ischemic stroke (2 papers, 2017 to 2025). A stroke disorder caused by obstruction of blood flow to the brain, due to thrombotic (local blood clot formation) or embolic (due to a blood clot or other material traveling from another site) event. "Remarkably, ischemic stroke was part of the initial presentation, suggesting that mevalonate kinase deficiency can manifest primarily through thrombo-inflammatory complications in adulthood, even in the absence of recurrent febrile episodes." (PMID 41112284, 2025).
pharyngitis (2 papers, 2013 to 2022). Inflammation of the throat most often caused by viral and bacterial infections. "Cases of pediatric periodic fever, aphthous stomatitis, pharyngitis and adenitis (PFAPA) have also been described in Sweden, but the disease is apparently not heritable; mevalonate kinase deficiency has not been diagnosed in ethnic Swedes." (PMID 24138840, 2013).
psoriasis (2 papers, 2023). An autoimmune condition characterized by red, well-delineated plaques with silvery scales that are usually on the extensor surfaces and scalp. "Although these three enzymes are proven to affect the function of KCs and psoriasis-related cytokines, there has been no research on the involvement of MVK, PMVK, and MVD in psoriasis." (PMID 37234169, 2023).
Smith-Lemli-Opitz syndrome (2 papers, 2021 to 2023). Smith-Lemli-Opitz syndrome (SLOS) is characterized by multiple congenital anomalies, intellectual deficit, and behavioral problems. "The pathogenesis of specific rare diseases such as Smith-Lemli-Opitz syndrome and mevalonate kinase deficiency may arise from enzymatic defects in components of the sterol biosynthetic pathway, resulting in a shortage of downstream products." (PMID 37761412, 2023). "Examples of such congenital disorders and the affected enzymes include Smith-Lemli-Opitz syndrome (SLOS; DHCR7, OMIM# 270400), desmosterolosis (DHCR24, OMIM# 602398), lathosterolosis (sterol-C5-desaturase, OMIM# 607330), and mevalonate kinase (MVK, OMIM# 251170) deficiency." (PMID 33662384, 2021).
vasculitis (2 papers, 2020 to 2021). "Next-generation sequencing revealed compound heterozygous mutation in MVK c.928G > A (p.V310M) and c.1129G > A (p.V377I) while reduced mevalonate enzyme activity was confirmed suggesting a diagnosis of MKD as a cause of the severe vasculitis." (PMID 34809655, 2021).
Behçet’s disease (1 paper, 2021). "Aphthous stomatitis accompanying recurrent fevers may also be part of rare syndromes like mevalonate kinase deficiency and Behçet’s disease (BD)." (PMID 33971891, 2021).
bone metastasis (1 paper, 2023). Transfer of a neoplasm from its primary site to bones. "This enzyme acts downstream of MVK, and ZA is given to patients with osteoporosis and bone metastasis in the clinic." (PMID 36657447, 2023).
CHARGE syndrome (1 paper, 2026). CHARGE syndrome is a multiple congenital anomaly syndrome characterized by the variable combination of multiple anomalies, mainly Coloboma; Choanal atresia/stenosis; Cranial nerve dysfunction; Characteristic ear anomalies (known as the major 4 C's). "Additionally, one 22q11.21 microduplication and four monogenic disorders were identified: CHARGE syndrome, Beckwith–Wiedemann syndrome, Meckel–Gruber syndrome, and mevalonate kinase deficiency." (PMID 40814105, 2026).
coronary heart disease (1 paper, 2016). "This study aimed to evaluate the associations between functional polymorphisms in three genes (MVK, MMAB and KCTD10) and HDL-C concentrations, as well as coronary heart disease (CHD) susceptibility in Chinese individuals." (PMID 27716295, 2016).
familial hypercholesterolemia (1 paper, 2023). An inheritable form of hyperlipidemia, in which there are excess lipids in the blood. "Non-destructive arthritis may be seen in mevalonate kinase deficiency and familial hypercholesterolemia." (PMID 37563694, 2023).
hepatoma (1 paper, 2021).
Intellectual disability (1 paper, 2024). "A registry analysis from Eurofever, which included 114 cases of mevalonate kinase deficiency, reported cerebellar syndrome in two patients (1.7%) and intellectual disability in two others (1.7%), with headache being the most common neurological symptom, occurring in 43 patients (37.7%)." (PMID 39176373, 2024).
intestinal obstruction (1 paper, 2025). Blockage of the normal flow of the intestinal contents within the bowel. "This case shows that intestinal obstruction with dilated fetal bowel loops can be an initially leading clinical symptom of severe mevalonate kinase deficiency." (PMID 40038796, 2025).
lepromatous leprosy (1 paper, 2021). A chronic communicable infection which is a principal or polar form of leprosy. "Furthermore, we observed a prominent upregulation toward higher MOI (100:1) when genes associated with cholesterol and fatty acid metabolism (DHCR7, MVK, and MSMO, and LACC1/FAMIN were analyzed, which are pathways involved in lepromatous leprosy immunopathogenesis." (PMID 33936067, 2021).
lung carcinoma (1 paper, 2022). "Our findings indicate that the MVK, GGPS1 and PMVK expression was correlated with HMGA1 gene expression in lung cancer tissues, but not in normal lung tissue." (PMID 35805937, 2022).
melanoma (1 paper, 2022). A malignant, usually aggressive tumor composed of atypical, neoplastic melanocytes. "The relevance of SCD1, MVK, FASN and DHCR24 in melanoma progression or drug resistance is already supported by our previous studies and by the literature." (PMID 35912092, 2022).
mesothelioma (1 paper, 2023). A usually malignant and aggressive neoplasm of the mesothelium which is often associated with exposure to asbestos. "Furthermore, the elevated expression of MVK is also associated with poor survival among patients with mesothelioma (p = 0.004)." (PMID 36657447, 2023).
pancreatic cancer (1 paper, 2017). "In particular, we observed normalization of expression of KRAS, which is directly related to pancreatic cancer progression, and mevalonate pathway related genes (HMGCS1, MVD, MVK, and PDSS1)." (PMID 29262834, 2017).
polymicrogyria (1 paper, 2024). A developmental brain abnormality characterized by an excessive amount of small convolutions on the surface of the brain and cognitive dysfunction. "The novel findings in our case, including polymicrogyria, present a challenge for explanation, as there is no established literature linking polymicrogyria with MVK gene mutations." (PMID 39176373, 2024).
retinal dystrophies (1 paper, 2025). "Indeed, 14 genes that are differentially bound by PRPF8Y2334N in RPE cells have been associated with various retinal dystrophies and four genes (MVK, PDSS1, MERTK and SEMA4A) are involved in RP." (PMID 40045025, 2025).
retinitis pigmentosa (1 paper, 2023). Retinitis pigmentosa (RP) is an inherited retinal dystrophy leading to progressive loss of the photoreceptors and retinal pigment epithelium and resulting in blindness usually after several decades. "For example, mutations in the mevalonic kinase (MVK) gene were found to affect the occurrence of retinitis pigmentosa (RP) through the mevalonate pathway." (PMID 37587267, 2023).
Skeletal myopathy (1 paper, 2019). "In turn, mevalonic aciduria caused by mevalonate kinase deficiency with a resultant drop in isoprenes is linked to skeletal myopathy." (PMID 31100888, 2019).
synovitis (1 paper, 2021). Inflammation of a synovial membrane. "Differences in MVK expression detected in synovial membranes suggests that the in situ activity of MVK in synovitis resolution happens earlier in time, as suggested by our pathway analysis and in vivo study." (PMID 34956173, 2021).
virus infection (1 paper, 2018). "The mRNA expression of these five genes, HMGCS1, HMGCR, MVD, MVK, and FDPS, was consistently decreased after M1 virus infection in both HCT-116 and SW1990 cell lines." (PMID 29670091, 2018).